FOXA2 (forkhead box A2)
Diseases named in the same sentence as FOXA2 in open-access papers (continued):
Sharing a sentence is not in itself a finding about the gene and the disease.
Barrett esophagus (4 papers, 2017 to 2021). Esophageal lesion lined with columnar metaplastic epithelium which is flat or villiform. "Previous studies have suggested a role for FOXA2 in promoting Barrett's metaplasia, and further studies are warranted to assess whether FOXA proteins act more widely in a pioneering capacity to drive this transition." (PMID 30962179, 2019). "The metaplastic effect of HH on squamous esophageal epithelium is mediated by upregulation of FOXA2: FOXA2 was found to be overexpressed in Barrett’s metaplasia, dysplasia and EOC, while it was not expressed in ESCC." (PMID 28930282, 2017).
bladder cancer (4 papers, 2012 to 2024). "To determine the extent of FOXA1 and FOXA2 expression in various stages of bladder cancer, we performed immunohistochemical analysis on human tumor samples." (PMID 22590586, 2012). "One potential mechanism could be that the mutated segments cover specific bladder cancer-related pathogenic genes, such as TP73, KMT2C, and FOXA2, or affect some tumor suppressor genes." (PMID 39349436, 2024).
cholangiocarcinoma (4 papers, 2019 to 2025). A carcinoma that arises from the intrahepatic biliary tree (intrahepatic cholangiocarcinoma) or from the junction, or adjacent to the junction, of the right and left hepatic ducts (hilar cholangiocarcinoma). "The expressions of FoxA2 and FoxA3 in cholangiocarcinoma were at similar levels with those in colon adenocarcinoma, liver hepatocellular carcinoma, pancreatic adenocarcinoma, rectum adenocarcinoma, and stomach adenocarcinoma." (PMID 32151057, 2020). "Before-treatment and on-treatment biopsies were compared, revealing that mtIDH1 inhibition induced a more differentiated morphology of cholangiocarcinoma cells on H&E staining and the expression of hepatocyte lineage markers HNF-4α, FOXA1 (HNF-3α), FOXA2 (HNF-3β), and PPARA." (PMID 34967233, 2022).
glioma (4 papers, 2018 to 2023). A benign or malignant brain and spinal cord tumor that arises from glial cells (astrocytes, oligodendrocytes, ependymal cells). "The main mechanism is that miR-124a overexpression decreases the level of target fork head box protein A2 (FOXA2) and leads to lipid accumulation in cells, so that glioma stem cells cannot effectively metabolize lipids, resulting in poisoning." (PMID 34540663, 2021). "Therefore, RT-qPCR and Western blotting analysis were performed to validate that STING inhibitor H-151 significantly suppressed the mRNA and protein levels of FOXA2 in glioma cells." (PMID 37031183, 2023). "Likewise, miR-146b, miR-124a, and miR-34a were introduced into glioma cells from transfected hBMSC-derived EVs and abrogated glioma growth by decreasing EGFR and NF-κB protein, silencing FOXA2 and downregulating MYCN, respectively." (PMID 34479611, 2021).
insulinoma (4 papers, 2010 to 2025). "FOXA2 was found to promote ACE2 transcription in 832/13 insulinoma cells or mouse pancreatic islets." (PMID 41280104, 2025). "Regulation of insulin secretion machinery and transcription factor Foxa2 in insulinoma cells." (PMID 20860821, 2010). "Preventing sumoylation by mutating the SUMO acceptor K6 to arginine resulted in downregulation of FOXA2 protein but not RNA expression in INS-1E insulinoma cells." (PMID 23118920, 2012). "FOXA2 protein but not mRNA levels are regulated in insulinoma cells by microRNA (miRNA) 124a." (PMID 23118920, 2012).
neuroendocrine tumor (4 papers, 2015 to 2024). "FOXA2 mutations encode a transcription factor found in neuroendocrine tumors, MYC-N may promote the appearance of the NEPC phenotype, FOXA1 is downregulated in NEPC, and its absence in cell line models of PCa triggers neuroendocrine differentiation." (PMID 37569304, 2023). "Compatible with key roles in the development of neuroendocrine tumors, MTC C cells differentially express the transcription factors Foxa1 and Foxa2, which are associated with tumor growth." (PMID 34208296, 2021). "Consistent with a key role in neuroendocrine tumor development, MTC cells differentially express transcription factors Foxa1 and Foxa2, correlating with tumor growth and invasion." (PMID 26395490, 2015).
prostate adenocarcinoma (4 papers, 2021 to 2024). "FOXA2 also has shown to have an alternate transcriptional program in NEPC compared to prostate adenocarcinoma, involving genes associated with neurogenesis, neurotransmission, and neuropeptide signalling, facilitated by cooperation with HIF-1α." (PMID 39682746, 2024). "In addition, we investigated the association of the expression of PHF8 and FOXA2 with pathological grade (Gleason scores) in 42 specimens with prostate adenocarcinoma." (PMID 33009820, 2021). "Concordant with the clinical expression profile of LINC00261, FOXA2 expression was significantly elevated in NEPC PDX models and NEPC patient tumors compared with prostate adenocarcinoma." (PMID 33793068, 2021). "FOXA2 was expressed only in the endometrial cell line, while FOXA1 was expressed only in the prostate cell line, in agreement with the tissue expression patterns and that most prostatic adenocarcinomas and LNCaP are of secretory (i.e., luminal) cell origin." (PMID 35703180, 2022). "The TF, Forkhead Box A2 (FOXA2) was discovered to have high expression in NEPC cell lines and PDX models compared to being absent or low-expressed in prostate adenocarcinoma, with its expression promoted by ADT." (PMID 39682746, 2024).
allergic asthma (3 papers, 2019 to 2026). A asthma with a basis in a pathological type I hypersensitivity reaction. "Our study suggests that Hh pathway activation and Foxa2 have opposing functions in lung T-cells, as Foxa2-deficiency increased Th2 differentiation, AAD severity and Smo expression, whereas Shh signalling promotes Th2 differentiation and allergic asthma." (PMID 36003391, 2022). "Notably, the expression of Foxa2 is suppressed both in mouse models and in humans with allergic asthma." (PMID 31881038, 2019). "Within the respiratory system, FOXA1, FOXA2, and FOXA3 have emerged as modulators of pulmonary inflammation, with important implications for the pathogenesis of allergic asthma." (PMID 41868652, 2026).
Alzheimer disease (3 papers, 2020 to 2025). A progressive, neurodegenerative disease characterized by loss of function and death of nerve cells in several areas of the brain leading to loss of cognitive function such as memory and language. "The expression of Foxa2 and nuclear receptor subfamily 4 group A member 2 (Nurr1) mediated by adeno-associated virus can alleviate cognitive deficits in mice with Alzheimer’s disease." (PMID 39859532, 2025).
breast tumors (3 papers, 2017 to 2023). "FOXA2 is implicated in increased relapses and risk prognostic value in triple-negative/basal-like breast tumors." (PMID 28852427, 2017). "In the SQ breast tumors, we observed significantly upregulated mRNA levels of the Oct3/4 regulatory network, including ONSS, and several other PTFs, including Nanog, Sall4, Sox2, Sox4, FoxA2, Gata6, Zic2 and HoxB7, as well as Oct3/4 isoform B, polycomb suppressors Bmi1, EzH2, Amigo and Dkk1." (PMID 37298091, 2023).
choriocarcinoma (3 papers, 2019 to 2025). An aggressive malignant tumor arising from trophoblastic cells. "Expression of FOXA2 is absent in the GCT cell lines TCam-2, 2102EP (EC), NCCIT (EC), and JAR (choriocarcinoma) as well as in the Sertoli cell line FS1 and adult fibroblasts (MPAF)." (PMID 31130628, 2019).
esophageal adenocarcinoma (3 papers, 2019 to 2021). A malignant tumor with glandular differentiation arising predominantly from Barrett mucosa in the lower third of the esophagus. "In addition, FOXA2 was upregulated in esophageal adenocarcinoma and worked as a potential indicator in the tumor development." (PMID 34551777, 2021).
Lung Squamous Cell Carcinoma (3 papers, 2015 to 2024). "FOXA2 activates RND1 to suppress the arachidonic acid metabolism pathway and cisplatin resistance in lung squamous cell carcinoma." (PMID 39129202, 2024).
lymph node metastasis (3 papers, 2019 to 2022). "The FOXA2 protein was mainly positively expressed in the nucleoplasm of OC cells and was associated with FIGO staging and lymph node metastasis." (PMID 35418998, 2022). "Despite the lack of statistical significance between both groups, the low FOXA2 expression group seemed to have a higher rate of lymph node metastasis (26.0 vs. 11.4%)." (PMID 31689237, 2019). "A univariate analysis showed that tumor size (p = 0.05), vascular invasion (p = 0.032), FoxA2 expression (p <0.001), positive margins (p = 0.004), lymph node metastasis (p <0.001) (P = 0.005), AJCC stage (p < 0.001), PLT (p = 0.003), and ALB (p = 0.007) were associated with relapse." (PMID 31689237, 2019).
neuroendocrine prostate tumors (3 papers, 2021 to 2024). "FoxA2 (neuroendocrine-specific transcription factor) was shown to promote tumorigenesis in cooperation with HIF1α in neuroendocrine prostate tumors." (PMID 39103560, 2024). "Notably, FOXA2 was critical to drive the formation of neuroendocrine phenotype and neuroendocrine prostate tumors." (PMID 38252148, 2024).
prostate tumors (3 papers, 2013 to 2024). "The shift from FOXA1 to FOXA2 expression represents a notable marker of lineage plasticity and disease progression within prostate tumors, highlighting a transition toward a more aggressive phenotype." (PMID 39470735, 2024). "In 2010, Ronai and his colleagues reported on the potential role of a hypoxia-mediated “FoxA2/HIF-1a” complex in driving NE phenotype in mouse prostate tumors, which is concordant with previous studies pointing out the preferential occurrence of FOXA2 expression in human NEPC." (PMID 24724054, 2014). "NE phenotype prostate tumor cells in TRAMP mice display similar morphological and molecular characteristics to human NED and NEPC cells, including the expression of IHC markers, synaptophysin, chromogranin A and FOXA2, and loss of expression of cytokeratin 8 (CK8)." (PMID 23620793, 2013).
atherosclerosis (2 papers, 2022 to 2025). A disease characterized by the build-up of fatty material and calcium deposition in the arterial wall resulting in partial or complete occlusion of the arterial lumen. "Three transcriptional regulators such as RXRA, SOX7, and FOXA2, that have been predicted to bind with SNP rs3136441 in the presence of allele C, may have the pathogenetic role for atherosclerosis." (PMID 35203469, 2022).
biliary atresia (2 papers, 2017 to 2023). A rare, biliary tract disease characterized by progressive obliterative cholangiopathy of the intra- and extrahepatic bile ducts, occurring in the embryonic/ perinatal period, leading to severe and persistent neonatal jaundice and acholic stool. "Other studies have demonstrated that mutations in FOXA2, GPC1, ADD3, PKD1L1, EFEMP1/3, STIP1, XPNPEP1, REV1 and JAG1 genes can increase an individual’s genetic susceptibility to biliary atresia." (PMID 37324459, 2023). "Other genes including FOXA2, GPC1, ADD3, PKD1L, EFEMP1/3, STIP1 were found to be associated with biliary atresia." (PMID 37324459, 2023).
cholestasis (2 papers, 2023 to 2024). Impairment of the bile flow caused by obstruction within the liver, or outside the liver in the bile duct system. "The extended list of FOXA2 targets contains high overexpression of the “molecular transporter” category, further supporting the phenotype that FOXA2 deficiency leads to reduced bile acid transporter expression and cholestasis." (PMID 36798663, 2023). "In mice fed standard chow, mild cholestasis due to the lack of FOXA2 in the liver was sufficient to induce endoplasmic reticulum stress." (PMID 36798663, 2023).
chronic lung disease (2 papers, 2013 to 2020). According to the definitions of the American and British Thoracic Societies, including pulmonary functional tests, X-rays, and CT scans for items such as fibrosis, bronchiectasis, bullae, emphysema, nodular or lymphomatous abnormalities. "These pathological features are commonly found in the airways of several chronic lung diseases, including cystic fibrosis, as well as in mouse airways deficient in the forkhead box A2 (FOXA2), a transcriptional repressor of goblet GCHM and mucus biosynthesis." (PMID 23915402, 2013). "Finally, detailed mechanistic characterization of how these drugs restore FOXA2 function may lead to new methods of controlling excessive mucus, lowering bacterial burden and improving the quality of life in patients with chronic lung diseases." (PMID 32269574, 2020).
colon adenocarcinoma (2 papers, 2020 to 2022). "Differentiated human colon adenocarcinoma cells have been found to correlate with decreased levels of FOXA2 upon treatment with shBMAL1." (PMID 36505412, 2022).
embryonal carcinoma (2 papers, 2015 to 2026). A non-seminomatous malignant germ cell tumor characterized by the presence of large germ cells with abundant cytoplasm resembling epithelial cells, geographic necrosis, high mitotic activity, and pseudoglandular and pseudopapillary structures formation. "DMSO-treated P19CL6 embryonal carcinoma cells transiently adopt a mesendodermal-like state, as judged by robust coexpression of Lhx1, Eomes, T, Foxa2, and Cxcr4." (PMID 26494787, 2015).
esophageal cancer (2 papers, 2020 to 2022). A primary or metastatic malignant neoplasm involving the esophagus. "Abnormal expression of FOXA1 and FOXA2 has been observed in multiple types of cancers, including prostate, breast, lung, and esophageal cancer." (PMID 35897813, 2022). "FoxA3 was also up-regulated and promoted metastasis in esophageal cancer cells through the regulations of FoxA1 and FoxA2 expressions." (PMID 32151057, 2020). "FoxA1, FoxA2 and FoxA3 play synergistic roles in metastasis of esophageal cancer." (PMID 32151057, 2020).
Hyperglycemia (2 papers, 2013 to 2021). An increased concentration of glucose in the blood. "The hypoglycemic episode followed by hyperglycemia during childhood due to FOXA2 mutations is similar to some MODY gene mutations such as ABCC844, HNF1A45, and HNF4A46." (PMID 33473118, 2021). "It is thus very likely that additional β-cell like cells needed were generated from the FoxA2 and/or Pdx1-positive fraction in vivo to eventually correct the hyperglycemia." (PMID 23671681, 2013). "Whether the defect in FOXA2 leads to hypo-or hyperglycemia is still controversial." (PMID 33473118, 2021).
leukemia (2 papers, 2019 to 2022). A malignant (clonal) hematologic disorder, involving hematopoietic stem cells and characterized by the presence of primitive or atypical myeloid or lymphoid cells in the bone marrow and the blood. "Both are GABAergic and can be distinguished based on the combinatorial expression of highly specific TFs: Forkhead Box A2 (Foxa2), GATA-binding factor 2/3 (Gata2/3), and Stem cell leukemia/T-cell acute leukemia 1 (Scl/Tal1)." (PMID 31641138, 2019).
metastatic tumors (2 papers, 2024 to 2025). "To better resolve the transcriptional programs associated with FOXA2, we analyzed single cell (sc) RNA-seq data from 19 metastatic tumors with FOXA2 expression in at least 200 tumor cells in each (age:39-73, Male 42%)." (PMID 40419484, 2025). "Firstly, we performed the TF enrichment analysis between primary tumors and metastatic tumors, and finally, seven TFs were identified as differentially expressed TFs, including CBX2, CDX2, FOXA2, KLF4, NANOG, NCAPG, and TFAP2A, which was demonstrated in a heatmap and a volcano plot." (PMID 38702698, 2024).
nonalcoholic steatohepatitis (2 papers, 2023 to 2024). "Moreover, Wang and colleagues indicates that the activation of the AMPK/Foxa2 pathway can upregulate the expression of medium-chain acyl-CoA dehydrogenase, thereby promoting fatty acid oxidation and reducing lipid accumulation in nonalcoholic steatohepatitis." (PMID 38084145, 2023). "Previous studies have shown that empagliflozin can effectively reduce lipid deposition and ameliorate nonalcoholic steatohepatitis via activating AMPK/FOXA2 signaling to upregulate MCAD expression; thus, MCAD may be a potential therapeutic target for the treatment of nonalcoholic steatohepatitis." (PMID 39063197, 2024).
osteoporosis (2 papers, 2022 to 2023). A condition of reduced bone mass, with decreased cortical thickness and a decrease in the number and size of the trabeculae of cancellous bone (but normal chemical composition), resulting in increased fracture incidence. "Osteoporosis is related to lncRNA‐neighboring enhancer of FOXA2 (NEF) and inversely correlated to ankylosing spondylitis (AS), implying that lncRNA‐NEF might also relate to AS." (PMID 35894706, 2022). "Restoring lncRNA-NEF (neighboring enhancer of FOXA2) expression can inhibit adipogenesis and promote osteogenesis in ADSCs via regulating the miR-155/PTEN axis in osteoporosis." (PMID 37848931, 2023).
osteosarcoma (2 papers, 2014 to 2020). A usually aggressive malignant bone-forming mesenchymal neoplasm, predominantly affecting adolescents and young adults. "High expression of CYP26B1, GP1BB, and IFI44 in osteosarcoma patients was correlated with good prognosis, while high expression of DDX10 and FOXA2 in osteosarcoma patients was associated with poor prognosis." (PMID 32284759, 2020). "Three of highly expressed genes (DDX10, FOXA2, and HEY1) were correlated with poor prognosis, while three of lowly expressed genes (CYP26B1, GP1BB, and IFI44) showed the opposite trend in patients with osteosarcoma." (PMID 32284759, 2020).
papillary thyroid carcinoma (2 papers, 2008 to 2019). "Next, we transfected either the HNF3β/FoxA2 or the TTF-1 expression vector into papillary thyroid carcinoma cell lines." (PMID 18682709, 2008). "Quantitative reverse transcription-polymerase chain reaction (RT–PCR) showed decreased expression of HNF3β/FoxA2 and TTF-1 mRNA in papillary thyroid carcinoma cell lines, when compared with normal thyroid cells." (PMID 18682709, 2008).
small cell lung carcinoma (2 papers, 2013 to 2025). Small cell lung cancer (SCLC) is a highly aggressive malignant neoplasm, accounting for 10-15% of lung cancer cases, characterized byrapid growth, and early metastasis. "Here, the authors discover that FOXA2, regulated by ASCL1, promotes multi-site metastasis in small cell lung cancer by inducing a fetal neuroendocrine gene expression program." (PMID 40419484, 2025).
triple-negative breast carcinoma (2 papers, 2019 to 2022). An invasive breast carcinoma which is negative for expression of estrogen receptor (ER), progesterone receptor (PR), and human epidermal growth factor receptor 2 (HER2). "FOXA2 has the function of promoting cell proliferation and cancer stem cell maintenance in triple-negative breast cancer." (PMID 31007610, 2019).
adenosquamous lung carcinoma (1 paper, 2018). An aggressive carcinoma with a poor prognosis characterized by a presence of both malignant squamous cells and glandular cells. "FoxA1 and FoxA2 are downregulated in the squamous component of murine and human adenosquamous lung carcinoma." (PMID 30475207, 2018).
amyotrophic lateral sclerosis (1 paper, 2014). Amyotrophic lateral sclerosis (ALS) is a neurodegenerative disease characterized by progressive muscular paralysis reflecting degeneration of motor neurons in the primary motor cortex, corticospinal tracts, brainstem and spinal cord. "A mutation in the FOXA2 gene was also significantly associated with the sporadic form of the motor neuron disease, amyotrophic lateral sclerosis (ALS)." (PMID 24406377, 2014).
atopic dermatitis (1 paper, 2019). "FOXA2 modulated the production of Th2 cytokines in mouse atopic dermatitis model via its action on T regs." (PMID 31555266, 2019).